PDIA4 (protein disulfide isomerase family A member 4)
Synonyms: ERp70; ERp-72; ERp72
Tractability: Antibody: UniProt predicts a signal peptide or a membrane-spanning region. PROTAC: ubiquitination databases record sites on it; its protein half-life has been measured; a small molecule that binds it is known.
Target class: Isomerase; Enzyme
Gene: Protein-coding gene on chromosome 7 (149,003,046 to 149,028,662, reverse strand). Ensembl gene ENSG00000155660.
Subcellular location: Endoplasmic reticulum lumen; Melanosome
Subcellular location (Human Protein Atlas): Endoplasmic reticulum
Gene Ontology:
Molecular function: protein binding; protein-disulfide reductase activity; RNA binding; protein disulfide isomerase activity
Biological process: protein folding; protein secretion
Cellular component: cell surface; endoplasmic reticulum; endoplasmic reticulum lumen; extracellular region; melanosome
Genetic constraint (gnomAD): Loss-of-function variants: 30 observed, 61.01 expected, observed/expected ratio (o/e) 0.49, 90% interval 0.37 to 0.67. The upper end of that interval is the gene's LOEUF score, 0.67, which puts it in group 2 of 6, group 1 being the genes least tolerant of losing a copy. Missense variants: 799 observed, 825.28 expected, observed/expected ratio (o/e) 0.97, 90% interval 0.91 to 1.03. Synonymous variants: 339 observed, 328.32 expected, observed/expected ratio (o/e) 1.03, 90% interval 0.94 to 1.13.
Homologues: Orthologues: chimpanzee PDIA4 (99% identical), macaque PDIA4 (98% identical), guinea pig PDIA4 (90% identical), rabbit PDIA4 (89% identical), mouse Pdia4 (88% identical), rat Pdia4 (88% identical), pig PDIA4 (88% identical), dog PDIA4 (84% identical), zebrafish pdia4 (73% identical), tropical clawed frog pdia4 (71% identical), Caenorhabditis elegans pdi-1 (23% identical), Caenorhabditis elegans ZK973.11 (13% identical), and 2 more. Paralogues in human: PDIA3 (32% identical), P4HB (25% identical), PDIA2 (23% identical), PDILT (18% identical), PDIA5 (17% identical), TXNDC5 (16% identical), PDIA6 (16% identical), ERP44 (14% identical), TMX3 (14% identical), TXNDC11 (13% identical), TMX1 (8% identical), ERP27 (8% identical), and 1 more.
Diseases named in the same sentence as PDIA4 in open-access papers:
PDIA4 is named in the same sentence as 65 diseases in open-access papers, as found by Europe PMC text mining. Sharing a sentence is not in itself a finding about the gene and the disease. The quoted sentences say what the papers report.
glioma (13 papers, 2020 to 2025). A benign or malignant brain and spinal cord tumor that arises from glial cells (astrocytes, oligodendrocytes, ependymal cells). "Several studies have shown that PDIA4 is overexpressed in human malignancies, including esophageal squamous cell carcinoma, and high levels of PDIA4 expression were associated with poor glioma survival rates." (PMID 38167446, 2024). "In addition, elevated PDIA4 expression has been associated with poor prognosis in several cancer types, including glioma, renal cell carcinoma, cervical cancer, and others." (PMID 41120732, 2025). "Research indicates that elevated levels of PDIA4 correlated with unfavorable outcomes in several cancers, including glioma, lung cancer, and breast cancer." (PMID 41185082, 2025). "The necroptosis-related gene (NRG) PDIA4 was thought to be interrelated with glioma-related immune cells, such as CD8+ T cells, Tregs, and eosinophils." (PMID 36111134, 2022). "The protein expression of P4HB and PDIA4 were higher in glioma tissues compared to normal brain tissues." (PMID 32023222, 2020). "Additionally, it was found that the knockdown of PDIA-4 resulted in significantly lower cell proliferation in glioma cells." (PMID 38612722, 2024). "Our research demonstrated that PDIA4 is distinctly low-expressed in glioma cells." (PMID 36111134, 2022). "Besides, the P4HB and PDIA4, which have significant prognostic value in gliomas, were also the important components of the ER stress-related signature." (PMID 34307339, 2021). "We found that knockdown of the P4HB and PDIA4 could significantly reduce the proliferation and migration of glioma cell lines in vitro." (PMID 34307339, 2021). "Besides, CCK-8 and clonogenic assays indicated that proliferative capacity and clonogenicity of glioma cell lines were attenuated after transfection with PDIA4 or P4HB siRNA." (PMID 34307339, 2021). "Previous studies have reported the involvement of PDIA4, MXRA8, PDLIM4, C9orf64, and GZMB in glioma patients’ poor prognosis through bioinformatics analysis." (PMID 38159261, 2023). "But, the RT-qPCR results showed that five genes (IKBKB, PDIA4, RCC2, RPL4, and TXNIP) were low expressed in glioma cell lines compared to HA." (PMID 36111134, 2022). "All four genes, P4HB, PDIA4, PDIA5, and TXNDC12, were expressed in glioma cell lines, and these genes were differentially expressed in different cell lines (U251, T98G, A172, U343)." (PMID 32023222, 2020). "The qRT-PCR and immunohistochemistry confirmed that P4HB, PDIA4 and PDIA5 were overexpressed in gliomas." (PMID 32023222, 2020). "Meanwhile, it is also indicated that anti-PDIA4 and/or anti-P4HB therapy may be a novel approach for glioma treatments." (PMID 34307339, 2021). "Serval recent researches has pointed out that P4HB and PDIA4 correlated with the malignant progression of glioma, but these conclusions have not been sufficiently verified by in vitro experiments." (PMID 34307339, 2021). "Similarly, PDIA4 was also found to upregulate in ESCC, glioma and so on." (PMID 38029391, 2023).
ovarian carcinoma (8 papers, 2017 to 2025). A malignant neoplasm originating from the surface ovarian epithelium. "In this study, we aimed to determine the underlying mechanism of the lncRNAs FAM225B and PDIA4 in ovarian cancer development." (PMID 37720188, 2023). "The expression levels of long non-coding RNA FAM225B and protein disulfide isomerase family member 4 (PDIA4) are reduced in ovarian cancer cells." (PMID 41322492, 2025). "The expression of lncRNAs FAM225B and PDIA4 was decreased in the serum of patients with ovarian cancer and cell lines." (PMID 37720188, 2023). "RT-qPCR and Western blot assays were performed to detect the expression levels of the lncRNAs FAM225B, DDX17, and PDIA4 in the serum of patients with ovarian cancer and cell lines." (PMID 37720188, 2023). "Especially, downregulated PDIA4 has been observed in patients with platinum-resistant ovarian cancer." (PMID 37720188, 2023). "In conclusion, the main findings of our study indicate that lncRNA FAM225B plays an inhibitory role in ovarian cancer via the DDX17/PDIA4 axis." (PMID 37720188, 2023). "To determine if FAM225B regulates PDIA4 expression in ovarian cancer, we tested the phenotypes of the cells after transfection or cotransfection with lncRNA FAM225B- and PDIA4-related vectors." (PMID 37720188, 2023). "First, lncRNA FAM225B and PDIA4 expression levels in the serum of patients with ovarian cancer (cancer group) and HCs were determined using RT-qPCR and Western blot assays." (PMID 37720188, 2023). "Downregulation of PDIA4 expression counteracts the suppressive effect of lncRNA FAM225B overexpression in ovarian cancer cells." (PMID 37720188, 2023). "To further verify the differential expression of FAM225B and PDIA4 in ovarian cancer cells, we tested their expression levels in ovarian cancer cell lines." (PMID 37720188, 2023). "At the same time, serum level of PDIA4 was declined in ovarian cancer patients in contrast to healthy people (p < .01)." (PMID 33159506, 2021). "Evidence has shown that that PDIA4 is lowly expressed in platinum‐resistant ovarian cancer patients." (PMID 33159506, 2021). "Considering the downregulated expression of PDIA4 in ovarian cancer as previously reported, we only transfected the overexpressed PDIA4 plasmid pcDNA3.1‐PDIA4 or control plasmid pcDNA3.1 into OVCAR3 and SKOV3 cells." (PMID 33159506, 2021). "In this current study, we discovered that miR‐378a‐3p promoted ovarian cancer cell growth via negatively modulating PDIA4 and PI3K/AKT pathway." (PMID 33159506, 2021). "Meanwhile, upregulated PDIA4 trended toward a decrease in cell proliferation, migration, and invasion (all p < .01), implying that PDIA4 plays a part in the suppression of ovarian cancer cell growth." (PMID 33159506, 2021). "In conclusion, this study highlights that miR‐378a‐3p plays an oncogenic role in ovarian cancer cell development through modulation of the PDIA4‐mediated PI3K/AKT pathway." (PMID 33159506, 2021). "It is concluded that miR‐378a‐3p contributes to promote the growth of ovarian cancer cells by restricting PDIA4 expression." (PMID 33159506, 2021). "This study provides evidences that miR‐378a‐3p activates PI3K/AKT signaling pathway by modulating PDIA4 expression, thereby playing a role in promoting the growth of ovarian cancer cells." (PMID 33159506, 2021). "The aim of this study was to probe into the effects of miR‐378a‐3p and protein disulfide‐isomerase A4 (PDIA4) on the biological functions of ovarian cancer cells." (PMID 33159506, 2021). "This study aimed to explore the roles and mechanisms of lncRNA FAM225B and PDIA4 in ovarian cancer." (PMID 37720188, 2023). "To determine whether PDIA4 participates in the molecular mechanism of lncRNA FAM225B in the development of ovarian cancer, we predicted that lncRNA FAM225B would inhibit PDIA4 expression by binding to the transcription factor DDX17." (PMID 37720188, 2023). "This suggests that FAM225B and PDIA4 are involved in ovarian cancer." (PMID 37720188, 2023).
ovarian carcinoma (continued). "Similarly, in our study, the downregulation of PDIA4 was observed in ovarian cancer, and the restoration/downregulation of PDIA4 contributed to the restriction/promotion of ovarian cancer cell progression." (PMID 37720188, 2023). "It was hypothesized that the lncRNAs FAM225B and PDIA4 expression were reduced in ovarian cancer cells compared with HOSEPIC cells (P < 0.01)." (PMID 37720188, 2023). "Meanwhile, a recent study pointed out that PDIA4 may be regarded as a biomarker for the treatment of ovarian cancer." (PMID 35678681, 2022). "Next, we then verified the effect of PDIA4 on the growth of ovarian cancer cells." (PMID 33159506, 2021). "The next step was to probe into whether miR‐378a‐3p regulated PDIA4 expression to modulate ovarian cancer cell progression." (PMID 33159506, 2021). "Similarly, our study found that PDIA4 expression was reduced in ovarian cancer cells versus that of HOSE cells (p < .01)." (PMID 33159506, 2021). "It is suggested in a study that DIA4 was downregulated in drug‐resistant ovarian cancer tissues relative to the sensitive ones, and inhibited PDIA4 predicted shorter disease‐free survival and overall survival in both the tested surgical specimens and the TCGA cohort." (PMID 33159506, 2021). "A recent study has pointed out that PDIA4 might be considered as therapeutic biomarkers for managing ovarian cancer." (PMID 33159506, 2021). "miR‐378a‐3p was elevated and PDIA4 was decreased in ovarian cancer cells and serum." (PMID 33159506, 2021). "Notably, PDIs play significant roles in cancer progression, and PDIA4 might be a therapeutic marker for managing ovarian cancer." (PMID 37720188, 2023). "Additionally, in ovarian cancer, PDIA4 could activate PI3K/AKT signaling to promote the growth of ovarian cancer cells through mediating miR-378a-3p." (PMID 38029391, 2023). "Furthermore, we wanted to elucidate through which signaling pathway that miR‐378a‐3p and PDIA4 played a role in ovarian cancer, and corresponding findings suggested that miR‐378a‐3p stimulated ovarian cancer cell growth by downregulating PDIA4 and activating PI3K/AKT pathway." (PMID 33159506, 2021). "In ovarian cancer cells, the binding of FAM225B to DDX17 upregulates the expression of PDIA4, which in turn inhibits the progression of ovarian cancer cells." (PMID 41322492, 2025). "DDX17 as a transcription factor, binds to the PDIA4 promoter to promote transcription, and restoration of PDIA1 expression inhibits the malignant phenotype of ovarian cancer cells." (PMID 39022688, 2024). "This research study supports the fact that lncRNA FAM225B in ovarian cancer can upregulate PDIA4 by directly binding to DDX17, inhibiting the activities of ovarian cancer cells." (PMID 37720188, 2023). "The results suggest that the lncRNA FAM225B can increase PDIA4 expression by combining with DDX17, inhibiting the process of ovarian cancer." (PMID 37720188, 2023). "In this study, we demonstrated that lncRNA FAM225B elevates PDIA4 by directly binding to DDX17, restricting the biological function of ovarian cancer cells." (PMID 37720188, 2023). "To determine the effect of PDIA4 on ovarian cancer cells, we transfected SKOV3 and OVCAR-3 cells with PDIA4-related vectors." (PMID 37720188, 2023). "Therefore, in ovarian cancer, lncRNA FAM225B promotes PDIA4 expression through DDX17, which in turn inhibits ovarian cancer progression." (PMID 39022688, 2024). "However, the functions of miR‐378a‐3p, PDIA4, and PI3K/AKT pathway in ovarian cancer progression need further confirmation." (PMID 33159506, 2021). "However, it is not apparent whether DDX17 regulates PDIA4 in ovarian cancer cells." (PMID 37720188, 2023).
Obesity (7 papers, 2017 to 2024). Accumulation of substantial excess body fat. "Recently, our report revealed the clinical insulin sensitizer metformin modulates PDIA4 and adiponectin expression and improves obesity-associated conditions in both in vitro adipocytes and in vivo mouse models." (PMID 36619574, 2022). "In this study, we demonstrated that PDIA4 is associated with obesity, insulin resistance and dyslipidemia, and that it was positively associated with the expression of MetS in our study population." (PMID 28650993, 2017). "In this study, we conducted comprehensive phenotyping of a previously unrecognized factor, Pdia4, in glucose homeostasis in two mouse models of obesity‐related diabetes." (PMID 34542937, 2021). "The findings presented further suggest the potential of Pdia4 to serve as a therapeutic target for obesity‐related diabetes and β‐cell pathology." (PMID 34542937, 2021). "Given the relationship between Pdia4 and obesity, it should be noted that other factors like aquaporins, a central player in fat metabolism, could be involved in the Pdia4 pathways." (PMID 36935456, 2023). "Consistently, serum Pdia4 was shown to be related to obesity, insulin sensitivity, and diabetes." (PMID 36935456, 2023). "For example, obesity-induced ERS in visceral adipocytes reduced adiponectin expression mainly through the inhibition of transcription activity by ER chaperone protein disulphide-isomerase A4 (PDIA4)." (PMID 38129878, 2023). "In this study, we found that PDIA4 level, this new ER stress protein, may contribute to the development of obesity-mediated adverse effects that result in clustering of insulin resistance, glucose intolerance, dyslipidemia and hypertension." (PMID 28650993, 2017). "However, the role of Pdia4 in obesity progression remains poorly understood." (PMID 36935456, 2023). "Given the importance of Pdia4 for obesity, it will be absolutely necessary to further explore the function and mechanism of PS1 in obesity." (PMID 36935456, 2023).
breast carcinoma (6 papers, 2020 to 2025). "The inhibition of PDIA-1, an isoform of PDIA-4, in breast cancer cells and endothelial cells resulted in a significantly slower migration rate compared to the control." (PMID 38612722, 2024). "In a subclass analysis of breast cancer, PDIA4 mRNA expression was significantly higher in TNBC than in luminal and Her-2 positive cancers in UALCAN database." (PMID 38167446, 2024). "Both PDIA6 and PDIA4 protein levels were notably upregulated in primary breast cancers, compared to normal adjacent breast tissues." (PMID 37705743, 2023). "Furthermore, we performed western blots on 10 paired breast cancer tissues and normal tissues to examine the protein level of PDIA4." (PMID 38167446, 2024). "We further found that the expression levels of PDIA6 and PDIA4 were higher in breast cancer tissues compared to normal breast tissues, with the highest level observed in the TNBC subtype, suggesting that PDIA6 and PDIA4 could serve as prognostic markers and therapeutic targets for TNBC." (PMID 37705743, 2023). "More specifically, out of 21 members, PDIA1, PDIA3, PDIA4, and PDIA6 are identified to exhibit an increased mRNA level in breast cancer, according to the Gene Expression Atlas dataset." (PMID 35159012, 2022). "For example, PDIA1 and PDIA6 are highly expressed in breast cancer cells (MDA-MB-231, MDA-MB-468, and T47D), whereas PDIA4 (ERp72) expression is high in those two TNBC cells but moderate in T47D cells, indicating a complex transcriptional regulation mechanism." (PMID 35159012, 2022). "Consistent with the findings, the mRNA levels of PDIA1, PDIA3, PDIA4, and PDIA6 are typically overexpressed in HER2-enriched and Basal-like breast cancer subtypes as evidenced by gene expression data attained from the Gene Expression Atlas datasets." (PMID 35159012, 2022). "Moreover, the analysis of breast cancer subtypes showed that TNBC tumors express the highest level of PDIA6 and PDIA4 proteins among all the subtypes examined." (PMID 37705743, 2023). "It remains to be established in further studies whether, apart from PDIA1, other PDIs including PDIA3, PDIA4 and PDIA6 displaying relative high expression in breast cancer cells and endothelium are also involved in regulating cancer cell interaction." (PMID 33023153, 2020).